RN7SL23P (RNA, 7SL, cytoplasmic 23, pseudogene)
Gene: Miscellaneous RNA gene on chromosome 11 (61,444,149 to 61,444,423, forward strand). Ensembl gene ENSG00000240823.
Homologues: Orthologues: chimpanzee Metazoa_SRP (99% identical). Paralogues in human: RN7SL1 (79% identical), RN7SL3 (79% identical), RN7SL2 (79% identical), RN7SL451P (77% identical), RN7SL448P (77% identical), RN7SL408P (77% identical), RN7SL587P (76% identical), RN7SL630P (76% identical), RN7SL743P (76% identical), RN7SL856P (76% identical), RN7SL230P (76% identical), RN7SL478P (76% identical), and 701 more.